RD3L (RD3 like)
Synonyms: TDRD9AS1; TDRD9-AS1
Tractability: No criterion of Open Targets' tractability assessment is met for any kind of drug.
Gene: Protein-coding gene on chromosome 14 (103,940,426 to 103,942,561, reverse strand). Ensembl gene ENSG00000227729.
Genetic constraint (gnomAD): Loss-of-function variants: 7 observed, 14.56 expected, observed/expected ratio (o/e) 0.48, 90% interval 0.27 to 0.9. The upper end of that interval is the gene's LOEUF score, 0.9, which puts it in group 3 of 6, group 1 being the genes least tolerant of losing a copy. Missense variants: 234 observed, 238.01 expected, observed/expected ratio (o/e) 0.98, 90% interval 0.88 to 1.1. Synonymous variants: 87 observed, 82.14 expected, observed/expected ratio (o/e) 1.06, 90% interval 0.89 to 1.27.
Homologues: Orthologues: chimpanzee RD3L (99% identical), macaque RD3L (95% identical), dog RD3L (87% identical), guinea pig RD3L (83% identical), pig RD3L (82% identical), mouse Rd3l (75% identical), rat Rd3l (73% identical), tropical clawed frog rd3l (66% identical), rabbit RD3L (65% identical). Paralogues in human: RD3 (25% identical).
Diseases named in the same sentence as RD3L in open-access papers:
RD3L is named in the same sentence as 3 diseases in open-access papers, as found by Europe PMC text mining. Sharing a sentence is not in itself a finding about the gene and the disease. The quoted sentences say what the papers report.
male infertility (1 paper, 2020). The inability of the male to effect fertilization of an ovum after a specified period of unprotected intercourse. "As well as being situated within RD3L, rs35337422 also lies within an intron of the overlapping TDRD9 gene (encoding ‘tudor domain containing 9’), which is implicated in male infertility." (PMID 32227305, 2020).
myopia (1 paper, 2020). "However, the functional data implicating the minor allele of rs35337422 as a deleterious missense variant for RD3L, makes a recessive effect shifting refractive error towards myopia the more likely option." (PMID 32227305, 2020). "Hence, the current approach of testing for non-additive effects provides further evidence, albeit circumstantial, linking the 3 variants to specific genes likely to have causal roles in myopia: ZMAT4, RD3L and LAMA2." (PMID 32227305, 2020).
retinal degeneration (1 paper, 2020). Degeneration of the retina. "Another common-specific gene, retinal degeneration 3 like (RD3L), encodes a domain of retinol degeneration (RD) 3 protein which is associated with retinal degeneration." (PMID 32903789, 2020).